EMP2 (epithelial membrane protein 2)
Diseases named in the same sentence as EMP2 in open-access papers (continued):
Sharing a sentence is not in itself a finding about the gene and the disease.
tumor (continued). "Moreover, tunel staining confirmed that FK002-exatecan effectively induces apoptosis of tumor cells with high EMP2 expression in the ADC administration group, indicating that FK002-exatecan could inhibit tumor growth by inducing apoptosis of tumor cells." (PMID 41173824, 2025). "Given the role of EMP2 in regulation of miRNAs involved in modeling the tumor microenvironment, it might be interesting to explore the impact of exosomes from EMP2-overexpressing cells on paracrine signaling and the behavior of cancer—associated fibroblasts in future studies." (PMID 33799364, 2021). "Nevertheless, our data suggest that EMP2 may exert tumor growth inhibitory effects in human NSCLC." (PMID 33799364, 2021). "The addition of EMP2 into CNE2 cells could reverse the tumor promotion effects of miR-101-3p mimic." (PMID 29050268, 2017). "Because EMP2 is a transmembrane protein, its downregulation might decrease the interactions with other proteins, including the membranous and nonmembranous in epithelial cells, and subsequently result in tumor progression in UBUC." (PMID 25940704, 2015). "In the group of high EMP2 expression, we observed that FK002-exatecan effectively restrains tumor growth in PTCs compared to the control group, and this effect was concentration-dependent." (PMID 41173824, 2025). "The role of EMP2 in HCC stem cells, drug resistance, and the tumor microenvironment remains uninvestigated." (PMID 39866225, 2025). "Thus, EMP2 might become a new target for tumor diagnosis and treatment." (PMID 36217151, 2022). "Using radiolabeled antibody fragments of EMP2, 64Cu-DOTA-EMP2, this tracer was able to detect tumor growth in a cell-line based Hec1a EC xenografts model in mice by PET." (PMID 31783595, 2019). "Genistein treatments, knockdown of EMP2 gene and double knockdown of CREB1 and EMP2 genes significantly inhibited tumor growth and notably downregulated CREB1 and EMP2 protein levels in the mice xenograft models." (PMID 25940704, 2015). "At both time points, HEC1A/EMP2 and wild-type tumors were clearly visualized, and a representative image at 20 h showed strong uptake in HEC1A/EMP2 tumor (white ellipse)." (PMID 22585360, 2013). "Statistical analysis revealed a significant inverse correlation of EMP2 and PMP22 expression in tumor tissues with differentiation grade (p = 0.005 and p = 0.019, respectively)." (PMID 21159173, 2010). "Our findings demonstrate a correlation between elevated EMP2 expression post-chemotherapy and reduced survival outcomes and reveal that targeting EMP2 in conjunction with chemotherapy yields a synergistic reduction in TNBC tumor volume." (PMID 38672563, 2024). "In our study, treatment with exosomes isolated from tumor cells transfected with EMP2 did not affect tumor cell migratory behavior, although the exosomes were shown to be successfully taken up by the cells." (PMID 33799364, 2021). "These genes likely function as downstream effectors of STAT3 in GBM to regulate not only cell proliferation (e.g., GAS7, IGFBP2, MEOX2 and MXI1), and but also tumor-stroma interactions by modulating protein secretion (e.g., ANXA1, ARL4C, EMILIN1, EMP2, EXTL3 and PDIA4)." (PMID 29774125, 2018). "At 20 h, which is the optimal time for minibody imaging, drawn ROIs revealed 10.2 ± 2.6 %ID/g ± SD in the HEC1A/EMP2 tumor, a 5.4-fold uptake ratio compared to that in the EMP2-negative tumor (1.9 ± 0.5)." (PMID 22585360, 2013). "Expression data of EMP1, EMP2, EMP3 and PMP22 were obtained from all tumor samples." (PMID 21159173, 2010). "Indeed, initial imaging studies using nonresidualizing anti-EMP2 antibody fragments (prepared with I-124 by the Iodogen method) produced poor retention in the EMP2-positive tumor xenografts (data not shown)." (PMID 22585360, 2013).
tumor (continued). "Moreover, the high ratio of EMP2-positive tumor relative to various normal tissues lacking EMP2 protein expression (e.g., soft tissue, heart, blood) suggests that EMP2 minibodies specifically and efficiently adhere to their antigen." (PMID 22585360, 2013). "In contrast, the EMP2-negative Ramos tumor had low minibody uptake." (PMID 22585360, 2013). "The DOTA-KS83 minibody was radiolabeled with 64Cu, and tumor targeting was evaluated in mice bearing HEC1A/EMP2, HEC1A, and Ramos (EMP2-negative) xenografts." (PMID 22585360, 2013). "Moreover, compared to the blank control (Control) group and the negative control (shNC), stable knockdown of EMP2 expression in HepG2 and Huh-7 HCC cells (shEMP2#2 and shEMP2#3) significantly reduced the migration of tumor cells through the basement membrane and into the lower chamber." (PMID 39866225, 2025).
cancer (22 papers, 2013 to 2025). A tumor composed of atypical neoplastic, often pleomorphic cells that invade other tissues. "Elevated EMP2 levels have been associated with cancer progression by regulating and administering cell membrane composition and angiogenesis." (PMID 36217151, 2022). "EMP2, a novel tumor-related protein, encodes an interesting integral tetraspan membrane protein that is vital for cancer progression, innate immune response and neutrophil transmigration." (PMID 34869721, 2021). "The level of EMP2 protein is positively associated with cancer progression, which is supported by findings that EMP2 is expressed in 67% of lymph node metastases and is linked with lymphovascular invasion." (PMID 31652725, 2019). "Increased expression of EMP2 has been linked to cancer progression by controlling cell membrane composition and blood vessel growth." (PMID 31492143, 2019). "Our comprehensive analysis of pan-cancer transcriptomic data from databases such as TIMER and Oncomine shows that EMP2 expression varies significantly across different cancers." (PMID 39866225, 2025). "Dysregulated expression of Emp2 has been observed in various cancers along with the downregulation of Emp2, leading to increased cancer growth and metastasis." (PMID 40429836, 2025). "Alterations in EMP2 have been observed across different cancer types, suggesting its significance in tumorigenesis." (PMID 41173824, 2025). "Increasing evidence highlights epithelial membrane protein 2 (EMP2) as a promising therapeutic target in various human cancers." (PMID 41173824, 2025). "Herein, we mainly summarized the structure, mutation, and modification sites of PMP22, EMP1, EMP2, and EMP3, as well as the diseases related to these proteins, especially cancer types." (PMID 36217151, 2022). "In this context, we highlight in this review the functional aspects of the EMP family members EMP1, EMP2, and EMP3 related to their pathophysiology, particularly where associated with cancer metastasis." (PMID 31652725, 2019). "EMP2 is currently being investigated as a novel target for cancer treatment and to reduce pathologic neovascularization." (PMID 31508419, 2019). "Membranous expression of EMP2 in urothelial cells of the ureter and EMP2 downregulation results in inferior cancer-related survivals (n = 171)." (PMID 25940704, 2015). "This all indicates that EMP2 may be a potential ADC therapeutic target in cancers exhibiting elevated EMP2 levels." (PMID 41173824, 2025). "This suggests that EMP2 may have distinct roles in the initiation and progression of different cancer types, potentially contributing to the understanding of various malignancies." (PMID 39866225, 2025). "EMP2 has emerged as a novel prognostic and predictive biomarker in various human cancers." (PMID 41173824, 2025). "Thus, EMP2 can act as a platform for integrin signal transduction in cancer cells and help cell adhesion to the extracellular matrix (ECM)." (PMID 36217151, 2022). "Analysis of the expression of nine miRNAs (miR-30d_2, miR-21, miR-802, miR-1301_2, miR-200a_1, miR-518-5p_1, miR-18a_2, miR-25_1, and miR-205_1) involved in cancer development in both exosomes and cell lysates from the EMP2 transfectants and mock cells was carried out." (PMID 33799364, 2021). "The detection of as few as 10 SKBR3 cancer cells isolated from a peripheral blood matrix (5 mL) was possible using the markers CK19, SCGB2A2, EpCAM, EMP2, MAL2 and PPIC." (PMID 36831613, 2023). "For example, the screened genes, such as EMP2 and BAG3, have become prevalent targets for cancer therapeutic studies, which have been discussed in the Results, but they were not included in the current cancer gene list." (PMID 34693378, 2021). "Among the differentially expressed genes in metastatic samples, we found 7 of 30 genes (MAPK13, XIAP, AHR, SPN, TER1, EMP2, NDUFC2) were cancer-related." (PMID 28009993, 2017). "EMP1, EMP2, and EMP3 have been reported as novel therapeutic targets in human cancer." (PMID 36936167, 2023).
cancer (continued). "Expression analysis revealed a different mRNA expression pattern of EMPs with significant downregulation of EMP1 (nine out of ten cell lines) and EMP2 (six out of ten cell lines), but significant upregulation of EMP3 in more than half of the cancer cell lines compared to HBEC." (PMID 33799364, 2021). "Considering that EMP1, EMP2, and EMP3 have been reported to play important roles in various malignant tumors, increased expression of EMP1 and EMP3, along with stromal cellularity and stromal atypia, imply that increased EMP expression in PT could suggest a higher malignant potential for PT." (PMID 32857809, 2020). "A panel of six genes (CCNE2, DKFZp762E1312, EMP2, MAL2, PPIC and SLC6A8) were over-expressed in cancer cell lines and were absent in healthy women." (PMID 29132396, 2017).
infection (3 papers, 2022 to 2025). The state of being infected such as from the introduction of a foreign agent such as serum, vaccine, antigenic substance or organism. "HepG2 and Huh-7 cells, which exhibited higher endogenous expression of EMP2, were selected, and shRNA-EMP2 lentiviral infection was conducted to screen for stable knockdown of EMP2 in HCC cell lines." (PMID 39866225, 2025). "Recently, expression of EMP2 (epithelial membrane protein 2) in ATI cells was shown to promote neutrophil influx following infection with K. pneumoniae." (PMID 36829255, 2023). "EMP2 has been shown to confer a potential therapeutic role against host infection." (PMID 36544093, 2022).
kidney disease (2 papers, 2019 to 2024). "We conclude that Emp2 is not highly expressed in glomeruli and that global genetic inactivation of Emp2 does not affect viability or cause proteinuric kidney disease in mice." (PMID 31508419, 2019). "Our data, in addition to published reports of suspicious variants of EMP2 in individuals without proteinuric kidney disease, suggest that mutations in EMP2 may not be solely responsible for the development of early-onset childhood NS as previously reported." (PMID 31508419, 2019).
gynecological tumors (1 paper, 2013). "Epithelial membrane protein-2 (EMP2) is a novel oncogene upregulated in a number of gynecological tumors." (PMID 22585360, 2013).
lung (1 paper, 2021). "In this study, ectopic expression of EMP2 resulted in decreased activity of AKT and increased activity of ERK in the lung ADC cell line H1299, while a slightly enhanced p-AKT level and reduced p-ERK1/2 level were observed in the SCC cell line H2170." (PMID 33799364, 2021).
EMP2 also shares sentences with these, for which no sentence is quoted: colon cancer (2 papers); colorectal cancer (2); age-related macular degeneration (1); cervical cancer (1); chlamydial infection (1); chronic hepatitis (1); ductal carcinoma in situ (1); endometrioid ovarian cancers (1); esophageal squamous cell carcinoma (1); gastric cancer (1); Hepatitis (1); Hyperglycemia (1); invasive ductal carcinoma (1); lung fibrosis (1); lung squamous cell carcinoma (1); mesenchymal tumors (1); nephropathies (1); nephrosis (1); prostate carcinoma (1); retinopathy of prematurity (1); squamous carcinoma (1); triple-negative breast carcinoma (1).